MICA (MHC class I polypeptide-related sequence A)
Diseases named in the same sentence as MICA in open-access papers (continued):
Sharing a sentence is not in itself a finding about the gene and the disease.
multiple myeloma (continued). "The multiple myeloma cell line IM9 highly expressed MICA, MICB, and ULBP4." (PMID 35965586, 2022). "Moreover, we found that MM patient-derived PCs cultured in autologous or heterologous BMSC-CM for 48h expressed higher levels of MICA than primary myeloma cells cultured in RPMI1640 medium alone." (PMID 35967396, 2022). "This suggests that c-MYC/IRF4/miR-125b interplay could be less effective in NB compared with multiple myeloma in terms of MICA induction." (PMID 31040907, 2019). "MICA is released in multiple myeloma, and MICA/B as well as ULBP-6 are shed from leukemic cells." (PMID 31474977, 2019). "Moreover, JQ1 increased the expression of MICA in multiple myeloma, since the downregulation of c-MYC leads to up-modulation of miR-125-5p and the consequent downregulation of its target gene IRF4, known as transcription repressor of MICA." (PMID 31040907, 2019). "In addition, MICA can be shed off the myeloma cell surface and reportedly down-regulate or block engagement of the activating NKG2D receptor on NK and T cells." (PMID 30455698, 2018). "In addition, it was found that inhibition of GSK‐3 increases NKG2D ligand MICA expression in multiple myeloma cells via a down‐regulation of STAT3 activation." (PMID 28165192, 2017). "Interestingly, Jinushi and coworkers have demonstrated that bortezomib-mediated upregulation of MICA in myeloma cells required the activation of DDR, since shRNA silencing of ATM or Chk-2 blocked ligand induction." (PMID 26161387, 2015). "Moreover, MICA shedding from the surface of myeloma plasma cells may promote downregulation of NKG2D expression on the surface of NK cells weakening the NK-mediated anti-tumor response." (PMID 33194767, 2020). "Certain studies have shown that specific drugs can upregulate the expression of NKG2D ligands, such as MICA/B and ULBP1‐3, in myeloma cells through DNA damage response pathways mediated by ATM and ATR." (PMID 40557764, 2025). "VPA has been shown to increase the expression of NKG2D ligands in myeloma cells via an ERK-dependent mechanism and to increase the expression of MICA/B in pancreatic cancer cells via a PI3K/Akt signal pathway." (PMID 39877353, 2024). "In March 2024, the anti-MICA/B antibody CLN-619, which inhibits shedding, received FDA approval for the treatment of relapsed/refractory multiple myeloma." (PMID 38612935, 2024). "Tumor cells, including myeloma cells, are known to express ligands for activating NK cell receptors such as the MHC I-related molecules MICA/B and ULBPs, which are both NKG2D ligands." (PMID 38731936, 2024). "We analyzed the morphology of the patient primary myeloma cells for expression levels of MHC I, MICA, MICB, ULBP1, ULBP2/5/6, HLA-E, CD38 (n = 12), CD112, CD155, ICAM-1 and PD-L1 (n =5) using flow cytometry." (PMID 35413499, 2022). "BM myeloma plasma cells from early-stage patients display low levels of MHC class I molecules and high levels of MHC class I related chain A (MICA) and are readily recognized by NK cells." (PMID 33194767, 2020). "Other groups demonstrated that high concentrations of the Hsp90 inhibitor 17-AAG (1 and 6 μM) up-regulate the cell surface density of MICA and MICB on multiple myeloma cells and Hodgkin’s lymphoma cells and thereby can enhance NK cell cytotoxicity." (PMID 25854583, 2015). "Although our study was not designed to investigate the role of activating ligands, analysis of the NKG2D ligands MICA/B and ULPB2 showed that most myeloma cell lines in our panel expressed at least one of these ligands." (PMID 25920521, 2015). "Also, the expression of MICA and MICB, ligands for the NK cell activating receptor NKG2D, augments after tinostamustine treatment in myeloma cell lines and primary myeloma cells." (PMID 38731936, 2024). "In fact our results indicate that ex vivo exposure of primary myeloma cells to tinostamustine does not generally augment the levels of CD38 but is able to increase the expression of MICA and MICB." (PMID 38731936, 2024).
multiple myeloma (continued). "In multiple myeloma cells, LXRs activation enhanced the NK cell-cytotoxicity activity by upregulating the NKG2D ligands, namely, MHC class I polypeptide-related sequence-A (MICA) and MICB respectively." (PMID 38550382, 2024). "Thus, the transcriptional repressor c-Myc of MICA and IRF4 is an inhibitor of MICA promoter activity in multiple myeloma cells." (PMID 37784183, 2023). "In addition, 2A9-MICA is a novel BiAb targeting BCMA and MICA, which effectively activated induced NK cells to kill BCMA+ human myeloma cells in a preclinical study." (PMID 36330495, 2022). "The data showed that primary myeloma cells expressed high levels of MHC I and MICA, indicating that T cells and CIK cells may mediate the cytotoxicity." (PMID 35413499, 2022). "In other study, valproic acid (VPA) induced the upregulation of MICA/B and ULBP2 in MM cell lines and patients’ myeloma cells, and, consequently, degranulation and cytotoxic activity of NK cells were enhanced in presence of VPA-pretreated myeloma cells." (PMID 33802806, 2021). "Of note, patients with multiple myeloma (MM), which occasionally evolves from MGUS, show lower MICA surface expression on MM cells and lower anti-MICA antibody levels but strongly increased sMICA levels, which may foster disease progression." (PMID 32582150, 2020). "In addition, an important role of ADAM10 in the regulation of MICA and MICB shedding in response to the treatment with genotoxic agents was demonstrated in multiple myeloma cell lines and in primary malignant plasma cells derived from patients." (PMID 32269567, 2020). "Other treatments proposed for enhancing MICA expression include sodium butyrate, matrix metalloproteinase inhibitor III, and phenylarsine oxide, all of which were recently shown, in multiple myeloma cell lines, to enhance MICA expression and increase cytotoxicity." (PMID 29724044, 2018). "In multiple myeloma cells, the LXRs activation by GW3965 hydrochloride and LXR-623 agonists enhanced the NK cell-cytotoxicity activity by upregulating the NKG2D ligands such as MHC class I polypeptide-related sequence-A (MICA) and MHC class I polypeptide-related sequence-B (MICB) respectively." (PMID 38550382, 2024). "Another recent study has reported that BETi can increase NK cell-activating ligand MICA expression via Brd4 inhibition-modulated downregulation of IRF4, a transcriptional repressor of MICA, leading to enhanced NK cell-mediated cytotoxicity against multiple myeloma cells." (PMID 36539410, 2022). "Moreover, on multiple myeloma cell lines, we did not see a change in the expression of stress-induced activating ligands MICA/B and ULBP1/2." (PMID 34203549, 2021). "A number of other studies have demonstrated the expression of MICA and/or ULBP2 in senescent cells derived from different cell types, namely human activated stellate cells, replicative senescent human umbilical vein endothelial cells and chemotherapy-induced senescent multiple myeloma cells." (PMID 26878797, 2016). "In addition to the increase in CD38 levels, we have demonstrated that tinostamustine augments the expression of several NKG2D ligands, especially MICA and MICB, in myeloma cell lines, an event that may also be beneficial when combining tinostamustine with immunotherapy treatments." (PMID 38731936, 2024). "Furthermore, three TFs highly expressed in multiple myeloma and pivotal regulators of malignancy-specific gene expression, the Ikaros family zinc finger protein-1 and -3 (IKZF1 and IKZF3) and IRF4, are potent repressors of MICA expression in this hematological cancer." (PMID 29662484, 2018).
cervical carcinoma (37 papers, 2008 to 2025). A carcinoma arising from either the exocervical squamous epithelium or the endocervical glandular epithelium. "Other polymorphisms at the same MICA exon 5 microsatellite sequence were also associated with cervical cancer." (PMID 34680286, 2021). "Cervical cancer is one of the earliest malignant diseases found to be associated with MICA polymorphisms." (PMID 30813924, 2019). "A recent Swedish GWAS found that the MICA A5.1 allele was associated with a 42% increase in cervical carcinoma risk." (PMID 31166958, 2019). "There is evidence that overexpression of MICA/B ligands, combined with other factors, is associated with the survival and prognosis of cervical cancer patients." (PMID 21631944, 2011). "Because patients with cervical cancer carrying the A5.1 allele have less membrane-bound MICA, this may impair their ability to alert the immune system to human papillomavirus infection or tumor changes and increase the risk of disease." (PMID 30813924, 2019). "A GWAS study in cervical cancer patients linked one MICA-adjacent region to the disease and identified a SNP (rs2516448) linked to the MICA-A5.1 frame-shift mutation, suggesting that this allele may cause impaired immune activation resulting in cancer development." (PMID 30984204, 2019). "For instance, in vitro experiments on cervical cancer displayed that the use of vorinostat (a histone deacetylase inhibitor) facilitates an increase in MICA expression, thereby enhancing NK cell toxicity against cervical cancer cells." (PMID 40888643, 2025). "Evidence confirmed that LINC00240 can enhance cervical cancer progression by inducing miR-124-3p/STAT3/MICA-mediated natural killer T (NKT) cell tolerance." (PMID 39595204, 2024). "The cytotoxic activity of NKT cells is facilitated by the LINC00240/miR124-3p/STAT3/MICA axis in cervical cancer." (PMID 37784183, 2023). "LINC00240 expression promoted cervical cancer progression via the induction of miR-124-3p/STAT3/MICA-mediated NKT cell tolerance." (PMID 33422052, 2021). "LINC00240 acts as an oncogene in cervical cancer progression by modulating the miR-124-3p/STAT3/MICA axis." (PMID 33422052, 2021). "Our results showed the presence of atypical markers on cervical cancer cells; some of them are molecules involved in tumour cell recognition such as MICA/B and CD95." (PMID 31198791, 2019). "The first GWAS of cervical cancer on mostly Swedish patients with cervical intraepithelial neoplasia (CIN) III revealed that rs2516448 C/T (near MICA), rs9272143 T/C (between HLA-DRB1 and DQA1), and rs3117027C/A (at HLA-DPB2) are associated with CIN III5." (PMID 30333560, 2018). "Invasive cervical cancer tissues had higher MICA/B, ULBP1, and RAET1E expression than CIN or normal cervical epithelial tissues (all p < 0.001)." (PMID 25510288, 2014). "Since their expression increases even in early stages of cervical cancer, MICA/B and ULBP1 expression can be used to identify precursor lesions (i.e., CIN) that are at high risk of developing invasive cervical cancer." (PMID 25510288, 2014). "Recently, we demonstrated increased soluble MICA levels in sera from patients with cervical cancer and precursor lesions as compared with healthy donors." (PMID 21631944, 2011). "We were further surprised when we found that epithelial human cervical cancer cell lines not only expressed MICA and MICB but also their receptor." (PMID 21477352, 2011). "Since in this study we did not examine the relevance of the proteolytic activity, it will be of particular importance to characterize the enzymatic activity with respect to cell surface MICA shedding in cervical cancer." (PMID 18208618, 2008). "To generalize our findings, we studied the impact of MMP‐9 on MICA/B in the Hela cervical cancer that is known to express high levels of MICA/B. Similarly, MMP‐9 also decreased cell surface expression levels of MICA/B in Hela cells and SB‐3CT counteracted the MMP‐9 effect." (PMID 34486239, 2021).
cervical carcinoma (continued). "The UK Biobank cervical cancer GWAS, which combined CIN3 and invasive cervical cancer, confirmed variants at HLA-DQA1 (rs9272050), MICA (rs6938453), and HLA-DQB1 (rs55986091), of which HLA-DQA1 (rs9272050) was also replicated at a genome-wide significance in the FinnGen biobank cohort." (PMID 34680286, 2021). "Our results support the role of HLA-DRB1 and MICA in the pathogenesis of cervical cancer." (PMID 24403192, 2014). "In a genome-wide association study, we have previously identified and performed the initial replication of three novel susceptibility loci for cervical cancer: rs9272143 upstream of HLA-DRB1, rs2516448 adjacent to MHC class I polypeptide-related sequence A gene (MICA), and rs3117027 at HLA-DPB2." (PMID 24403192, 2014). "However, functional experiments to elucidate the actual relevance of MICA/NKG2D pathway in cervical cancer will be necessary." (PMID 18208618, 2008). "Therefore, it will be interesting to investigate if soluble HLA-G is present in cervical cancer patients and especially, to examine if serum HLA-G and MICA altogether are able to deliver a death signal in immune cells." (PMID 18208618, 2008). "Furthermore, Vorinostat inhibited PI3K (p110α), p-PI3K p55, and p-Akt protein expression and upregulated major histocompatibility class I-related chain A (MICA) expression in vitro and in vivo, which promoted natural killer (NK) cell-mediated cervical cancer cell lysis." (PMID 33147762, 2020). "Thus, when identifying patients with cervical cancer at increased risk of tumor invasion and/or progression, examining the expression levels of ULBP1 or MICA/B via IHC may have utility." (PMID 25510288, 2014). "Furthermore, the levels of free-MICA in serum are increased in association with cervical cancer progression, which suggests that a significant factor that contributes to HPV persistence or tumor progression could be the presence of soluble MICA in the serum." (PMID 24169630, 2013). "Metformin has been reported to increase NK cell cytotoxicity by regulating the mRNA and protein expression of MICA and HSP70 on the surface of human cervical cancer cells via the PI3K/Akt pathway." (PMID 38358644, 2024). "NKT cell tolerance and cervical cancer progression is greatly promoted by LINC00240 regulation of STAT3 and MICA." (PMID 37346034, 2023). "In cervical cancer, a study has shown that LINC00240 can promote STAT3 expression by sponging miR-124-3p, and then STAT3 can inhibit MICA to reduce the cytotoxicity of NKT cells." (PMID 34425834, 2021). "For example, a small subpopulation of cervical cancer cells express the NKG2D receptor on the cell surface and secrete the ligands MICA/B and thereby induce tumour proliferation and probably use these molecules as an immunological escape mechanism." (PMID 31198791, 2019). "The expression of markers of the immune system such as CD95, MICA/B, CD39, CD73, NKp30, NKp46, CD44, CD24, NKG2A, and CTLA-4 was analysed by flow cytometry on cervical cancer cells INBL (HPV 18, stage IVB), HeLa (HPV 18), CaSki (HPV 16), and C33A (HPV-)." (PMID 31198791, 2019). "ULBP1 expression was correlated with MICA/B (p < 0.001) and ULBP2 (p = 0.002) expression in cervical cancer." (PMID 25510288, 2014). "We then performed IHC analysis of MICA/MICB, ULBP1, ULBP2, ULBP3, RAET1E, and RAET1G in 200 cervical cancer specimens, 327 high-grade CINs, 99 low-grade CINs, and 541 matched nonadjacent normal cervical epithelial tissue samples." (PMID 25510288, 2014). "Immunohistochemistry analysis revealed that MICA/B and ULBP1 were significantly upregulated in cervical cancer tissues compared to their corresponding normal tissues." (PMID 25510288, 2014). "Multivariate analysis indicated that MICA/B+/ULBP1+ (HR = 0.16, p = 0.015) and ULBP1+ (HR = 0.31, p = 0.024) are independent prognostic factors of disease-free survival in cervical cancer." (PMID 25510288, 2014).
cervical carcinoma (continued). "High expression of either ULBP1 or MICA/B and ULBP1 combined is an indicator of good prognosis in cervical cancer, suggesting their potential utility as prognostic tests in clinical assessment." (PMID 25510288, 2014). "Recently, it has been reported that activating NK cell receptor ligands MICA (NKG2D ligand) and CD155 (DNAM-1 ligand) are differentially expressed during the progression to cervical cancer." (PMID 19531227, 2009). "The aim of this study was to compare the levels of soluble MICA (sMICA) and NKG2D-expressing NK and T cells in blood samples from patients with cervical cancer or precursor lesions with those from healthy donors." (PMID 18208618, 2008). "Thus, LINC00240 significantly downregulates miR-124-3p, decreases MICA mRNA and protein expressions and reduces the cytotoxic activity of NKT cells by regulating STAT3 promoted cervical cancer progression in vitro and in vivo." (PMID 37784183, 2023). "For example, the administration of hydralazine and valproate can increase the expression of MICA and MICB ligands in the CaSki cervical cancer cell line and reduce their shedding to the supernatant, allowing NK attack; while cells without hydralazine and valproate are not susceptible to NK attack." (PMID 24169630, 2013). "Therefore, in the present study we performed a systematic analysis of the MICA and MICB expression in human cervical cancer cell lines." (PMID 21631944, 2011). "Our data on the preferential cell surface expression of MICA over MICB in SiHa cells are in agreement with a recent study examining activating NK ligands in various cell lines (including SiHa) and in tumor cells from patients with cervical cancer." (PMID 21631944, 2011). "It is interesting to note that MICA and MICB has a greater induction for proliferation of the myelomonocytic cell lines than in the cervical cancer ones, we think that this is due to the fact that the myelomonocytic cells presented a higher expression of the NKG2D receptor on their membranes." (PMID 21477352, 2011). "This study provides evidence that even when MICA and MICB share a high degree of homology at both genomic and protein levels, differential regulation of their expression and cell surface appearance might be occurring in cervical cancer-derived cells." (PMID 21631944, 2011). "The goal of this study was to describe the expression pattern of MICA and MICB at the molecular and cellular levels in human cervical cancer cell lines infected or not with human papillomavirus, as well as in a non-tumorigenic keratinocyte cell line." (PMID 21631944, 2011). "This study was focused on gaining a better understanding of MICA and MICB expression at the molecular and cellular levels in human cervical cancer cell lines infected or not with HPV and a non-tumorigenic keratinocyte cell line." (PMID 21631944, 2011).